STAT3 (signal transducer and activator of transcription 3)
Diseases named in the same sentence as STAT3 in open-access papers (continued):
Sharing a sentence is not in itself a finding about the gene and the disease.
tumor (continued). "Various STAT signaling pathways, such as STAT3 activation, have been well documented for their tumorigenic role, yet the role of STAT1 in tumor formation remains unclear." (PMID 38675812, 2024). "Similarly, pharmacologic inhibition of STAT3 or genetic depletion of CCL2 and CCL7 reduced pro-tumor CD45highCD11b+CD68+CD206+ macrophages in CT2A tumors." (PMID 38443336, 2024). "STAT3 signaling is essential for promoting the development of intratumor-terminally exhausted CD8+ T cells by enhancing their effector functions and survival, leading to better tumor control." (PMID 39402302, 2024). "Interestingly, in tumor cells, a protein-protein interaction between chaperones and STAT proteins has been described and enhanced Hsp70 activity increased STAT3 activity." (PMID 38474102, 2024). "Furthermore, EGFR/STAT3 and Notch signaling support self-renewal and proliferation of GBM stem cells to drive tumor progression." (PMID 39513361, 2024). "More recently, we further demonstrated that injection therapy of anti-IL-6R antibodies suppressed the tumor growth of SW480 xenograft and attenuated the proliferation marker Ki-67, along with down-regulating JAK/STAT3, PI3K/AKT, and MEK/ERK-1/-2 signaling pathways." (PMID 38256960, 2024). "OS tumor-derived microparticles promote the polarization of macrophages to an M2-like phenotype through TBK1-STAT6 signaling and mediate migration of OS cells through CCL18/STAT3 signaling." (PMID 39199574, 2024). "Finally, p27 phosphorylation also increased tumor-initiating stem cell abundance via PTPN12 repression, and Pyk2 driven STAT3 activation in vivo." (PMID 38886396, 2024). "In addition, W. coagulans MZY531 regulates the Bax/Bcl-2/caspase-3 and JAK2/STAT3 apoptosis pathways and PI3K/AKT/mTOR pathways, as well as TGF-β/SMAD4 autophagy pathways, thereby attenuating tumor growth." (PMID 39459634, 2024). "However, co-exposure of GBM cells to TmHg and TMZ reduced tumor growth-related factors, HIF-1α and VEGF, and p-STAT3." (PMID 39055895, 2024). "SHOX2 can also directly activate the tumor metastasis-related gene WASF3, recruit the signal transduction-related factor STAT3 at its promoter site, and form a molecular complex with STAT3, which collectively enhances the activity of WASF3, promoting tumor metastasis." (PMID 39289763, 2024). "Interestingly, a strong immunosuppressive loop was identified via TAM and STAT3 and NFkB pathways in TME which reverberated in a higher expression of tumor progression markers, and consequently in a poor clinical outcome." (PMID 39061137, 2024). "In conclusion, our study initially demonstrates the crucial involvement of ETHE1 in tumor angiogenesis and uncovers a previously unrecognized mechanism whereby ETHE1 facilitates TC45-mediated dephosphorylation of STAT3, thereby suppressing the oncogenic effects of STAT3 signaling in CRC." (PMID 39198402, 2024). "Importantly, western blot analysis showed that LA-conditioned PCa cells, upregulating DDR1 expression, when seeded on LA-induced tumor decellularized ECM, exhibit both higher DDR1 and STAT3 phosphorylation/activation." (PMID 38907027, 2024). "Moreover, an abundance of research has also substantiated that the activated STAT3 signaling pathway can promote the secretion of CXCL12 in both stromal cells and tumor cells." (PMID 38920657, 2024). "Furthermore, CD109 induces EGFR-mediated STAT3 phosphorylation, which supports SCC cell migration, proliferation, and the cancer stem cell phenotype in vitro, suggesting its role in enhancing tumor aggressiveness and inflammation." (PMID 39990858, 2024). "Tumor cells stimulate osteoclasts to release the ligand interleukin (IL)-19 for the IL receptor 20 subunit β (IL-20RB), which then triggers IL-20RB-expressing tumor cells to initiate downstream JAK1/STAT3 signaling." (PMID 39512767, 2024).
tumor (continued). "Furthermore, the interaction between the IL‐6/STAT3 pathway and the nuclear receptor PXR can synergistically modulate changes in the tumour microenvironment and mitigate resistance mechanisms." (PMID 39495702, 2024). "Treatment with ovatodiolide (a bioactive component of Anisomeles indica), alone or combined with cisplatin, significantly reduces tumor sphere formation, suppressing stemness and disrupting TME communication, and decreases EV cargos through mTOR, PI3K, STAT3, β-catenin, and miR-21-5p." (PMID 39200273, 2024). "Activated STAT3, by upregulating CXCL12, promotes tumor cell migration." (PMID 38920657, 2024). "It is hypothesized that IL-10 could phosphorylate and activate STAT1, STAT3, STAT5, and PI3K pathways, exerting apoptosis regulation and tumor progression functions on immune cells." (PMID 38279997, 2024). "Taken together, we could conclude that the inhibitory impact of FASN on ferroptosis was achieved via NF-κB/STAT3/GPX4 axis, thereby facilitating tumor growth and resistance to ADM in DLBCL." (PMID 39345091, 2024). "Additionally, WNT5 can interact with the Frizzled-2 receptor and activate STAT3 phosphorylation, independently of Janus kinase, a process that regulates EMT and promotes the metastasis of tumor cells." (PMID 38927059, 2024). "In SA region, the expression of IL-6, gp130, and JAK2 was lower in tumor tissues in IL-6+gp130+, IL-6+JAK2+, and IL-6+gp130+JAK2+ cells (P < 0.05); and the expression of IL-6R, CRP was also lower in tumor tissues in IL-6R+CRP+, IL-6R+STAT3+, and IL-6R+CRP+STAT3+cells (P < 0.05)." (PMID 38881895, 2024). "We found that STK24 deficiency in tumor cells significantly impaired the phosphorylation of AKT, but not STAT1 and STAT3 when cells were exposed to IFN‐γ." (PMID 38229183, 2024). "Activated STAT3, in turn, promotes CMTR1-driven cell growth and immune evasion by suppressing the expression of chemokines and pro-inflammatory factors, thus further advancing tumor progression." (PMID 39659524, 2024). "Targeting STAT3 prevents in vitro and in vivo tumor growth and metastasis without affecting normal cells, suggesting that STAT3 is a promising molecular target for CRC therapy." (PMID 38185635, 2024). "Moreover, previous studies in tumor cells have demonstrated that dimeric PKM2 complexed with b-catenin, STAT3, Oct4, NF-kB/p65, and HIF-1a to regulate the expression of target genes." (PMID 38483700, 2024). "This axis is instrumental in tumor progression, promoting tumor cell proliferation, autophagy, metastasis, and angiogenesis while inhibiting apoptosis, through pivotal signaling pathways, including MAPK, NF-κB, PI3K/AKT, ERK, and STAT3." (PMID 38529373, 2024). "In CCA tumor tissues, the expression of IL-6 was positively correlated with gp130, JAK2, and STAT3." (PMID 38881895, 2024). "Under hypoxia, the formation of nPD-L1/p-Stat3 complex increases the expression of GSDMC in different cancer cells, converting apoptosis to pyroptosis so as to promote tumor progression and suppress anti-tumor immune responses." (PMID 38654314, 2024). "IL10 promotes differentiation of Tregs, enhances tumor cell survival, proliferation, and metastasis by controlling antitumor immunity mostly through the STAT3 signaling pathway via the IL10 receptor (IL10R), whereas IL6 activates Th2 cells to promote tumor progression." (PMID 38592450, 2024). "Moreover, the levels of proteins involved in cell proliferation (p-Stat3, PCNA, Ki67, and cyclin D1) and cell migration (MMP2) were analyzed in the tumor tissues." (PMID 38441416, 2024). "Current research suggests that macrophages may promote EMT through signaling pathways such as IL-35/JAK2-STAT6-GATA3, IL6/Jak/Stat3/THBS1, or STAT3/miR-506-3p/FoxQ1, which facilitate the invasion, and metastasis of tumor cells." (PMID 39068459, 2024).
tumor (continued). "CMTM family proteins also exert their biological functions by signaling pathways that correlate with cell growth and migration, including the EGFR, WNT and JAK2/STAT3 signaling pathways, indicating that CMTM proteins are potential targets for altering tumor progression and metastasis." (PMID 38223763, 2024). "The IL-6/STAT3 signaling pathway may play an essential role in the TIME; IL-6-mediated STAT3 activation in the TME inhibits the functional maturation of DCs, thus activating effector T cells and blocking the emergence of anti-tumor immunity in cancers." (PMID 38361933, 2024). "From here, we understand the complexity of the cellular response when the JAK/STAT pathway is activated following receptor interaction with different ligands: for example, STAT3 and STAT5A/B are involved in tumor progression, while STAT1 exhibits a tumor-suppressive effect." (PMID 38927059, 2024). "Indeed, the tumour presented a massive overexpression of pro-inflammatory cytokines, comprising TNFA, IFN-γ, IL6-Jak-STAT3, and IL2-STAT5 signalling cascade." (PMID 39421445, 2024). "Additionally, curcumin shows promise in synergistically enhancing the anti-tumor activity of cisplatin on papillary thyroid cancer (PTC) cells and tumor stem cell-like cells by inhibiting STAT3 activity." (PMID 39507759, 2024). "This suggests that there may be more tumor-derived EVs that regulate and promote angiogenesis through the JAK/STAT3 pathway." (PMID 39596828, 2024). "In long-term DEN experiments, HLJ1 deletion enhances tumor proliferation and progression, accompanied by pronounced STAT3 phosphorylation in normal tissues rather than in tumor regions." (PMID 39738726, 2024). "Interestingly, the role of SOCS5, SOCS6, JAK2/STAT3, and PI3K/AKT pathways in DDP resistance of tumor cells has been well documented." (PMID 38439876, 2024). "As such, STAT3 mediates induction of immunosuppressive tumor-derived factors, including IL-10, IL-6, VEGF, and TGFβ which, in a positive feedback loop, amplifies STAT3 activation, generating a pathway for immune evasion by tumors with constitutive STAT3 activation." (PMID 38339245, 2024). "Furthermore, garcinol mainly acts as an inhibitor of cellular processes like proliferation via regulation of transcription factors NF-κB and JAK/STAT3 and the PI3K/AKT signaling pathway in tumor cells and experimental animal models." (PMID 38791932, 2024). "Additionally, tumor-derived exosomal-miR-6794-5p translocates to macrophages in the surrounding tumor microenvironment and activates the JAK1/STAT3 pathway by inhibiting SOCS1 expression, resulting in M2 polarization of macrophages." (PMID 38521953, 2024). "The combined treatment with sorafenib and STAT3 knockdown may affect the TME via the cGAS-STING-type I IFNs axis of DCs, activating anti-tumor immune responses." (PMID 38891056, 2024). "In addition, tumor-derived exosomal miR-6794-5p promoted M2 polarization and the secretion of IL-10 by macrophages by activating the JAK1/STAT3 pathway, ultimately promoting tumor malignancy." (PMID 38521953, 2024). "The strong potential of these classes of inhibitors was demonstrated in preclinical models of colorectal cancer treated in vivo with nanoparticles loaded with the STAT3 inhibitor BBI608, which resulted in enhanced infiltration of CD4+ and CD8+ TILs at tumor sites and tumor regression." (PMID 39281678, 2024). "Further investigation indicated that CASC2, as a tumor suppressor lncRNA, could directly regulate PIAS3 expression by acting as a ceRNA for miR-18a, leading to STAT3 inactivation and inhibiting in vitro and in vivo CRC tumor growth." (PMID 38185635, 2024). "The experiment revealed that low STAT3 and ACC1 expression effectively halted tumor growth." (PMID 38495496, 2024). "Thus, p27 is a master regulator of STAT3-driven CSC transcriptional programs, driving tumor initiation and metastasis in preclinical xenograft and genetic models." (PMID 38886396, 2024).
tumor (continued). "Thus, 10 μM was chosen as a non-toxic concentration to study the effects of HIS on the IL-6/STAT3/S100A9 pathway, excluding direct tumor growth interference." (PMID 39720595, 2024). "Hypoxia in glioblatoma associates with complex signaling patterns including activation of several pathways such as MAPK, PI3K-AKT/mTOR and IL-6/JAK/STAT3 with the master regulator HIF-1, which in turn drive particular tumor behaviors determining, in the end, treatment outcomes and patients fate." (PMID 38654280, 2024). "Activation of STAT1, STAT2, STAT3, STAT4, and STAT6 was observed in expanded bile duct epithelium and tumor cells, while expression of STAT5a and STAT5b was found in macrophages and connective tissues surrounding the tumor." (PMID 39290697, 2024). "In addition, we demonstrated the molecular mechanism by which NASP mediates DNA repair through ANXA2 in GBM, and observed the effect of combination treatment with the STAT3 pathway inhibitor, WP1066, and radiotherapy in tumor‐bearing mice models." (PMID 38605477, 2024). "The inhibitory effect of LLL12B on STAT3 was evaluated in both in vivo and in vitro studies, and the in vitro result revealed that LLL12B induced apoptosis and inhibited colony formation and cell migration, while suppressing tumor growth in vivo in TNBC cells." (PMID 38892472, 2024). "Activated signaling pathways such as STAT3, NF-κB, and ERK1/2 in tumor cells." (PMID 39906741, 2024). "Thus, both ER stress signaling and reduced STAT3 signaling play overlapping roles in regulating MCL1 and BCL-XL levels that regulates tumor cell viability after drug exposure." (PMID 38758815, 2024). "Our findings suggest that DBF4 may regulate tumor progression by influencing the ERBB signaling pathway and its downstream pathways including JNK/STAT3, MAPK, and PI3K/AKT signaling pathways." (PMID 38724606, 2024). "Since the established role of STAT3 pathway in the tumor angiogenesis, we first detected whether ETHE1 could influence the activation of STAT3." (PMID 39198402, 2024). "Notably, novel biomarkers beyond overexpression of STAT3 pY705 may provide a more comprehensive approach to guiding STAT3-directed treatments and may include upstream ligands such as IL-6 that could be serially monitored with the convenience of a blood test compared to serial tumor biopsies." (PMID 38339245, 2024). "Considering the intimate connection between epithelia-mesenchymal transition (EMT) and cancer stemness, we also found the expression of STAT3 and KLF4 were decreased in ADCY5 overexpressing cells (P < 0.001), suggesting ADCY5 was capable of inhibiting stemness of tumor cells." (PMID 39319137, 2024). "Prostaglandin E2 (PGE2), a product of COX-2, can activate MDSCs via STAT3 phosphorylation, leading to suppressed CD8+ T-cell proliferation, reduced cytotoxicity against tumor cells, and impaired macrophage phagocytosis of cancer cells through the EP4-PI3K-Akt-ND-1 signaling pathway." (PMID 39877377, 2024). "Over-activated STAT3 promotes the activation of oncogenic cytokines and growth factor receptors and induces the overproduction of cytokines such as IL-6 and EGF, which in turn promotes tumor invasion, migration, metastasis, and angiogenesis." (PMID 39598398, 2024). "The intricate network of TFs, including SOX2, OCT4, NANOG, KLF4, c-MYC,β-catenin, STAT3, NF-κB, HIF-1α and YAP/TAZ, is central to the maintenance of the stem-likeproperties of GSCs, which in turn drive tumor heterogeneity, therapeutic resistance, andrecurrence." (PMID 38716541, 2024). "On the other hand, the expression of genes TOP1, EGFR, STAT3, NR3C1, VEGFA, and AR was upregulated, which could promote tumor cell growth." (PMID 38297292, 2024).
tumor (continued). "The importance of IL-6 as a biomarker in various cancers is increasingly recognized, highlighting its role in oncogenesis and tumor progression, with TAM-derived IL-6 pivotal in activating the STAT3 cascade, thereby upregulating EMT-TFs and propelling tumor progression." (PMID 39286635, 2024). "and then animal proteins were extracted from lung tissue for western blot analysis, which further showed that succinate could increase the phosphorylation of STAT3 and promote EMT in tumor tissue." (PMID 38486162, 2024). "It is worth noting that miR-125b-5p is a vital suppressor miRNA that can target peroxiredoxins like 2 A (PRXL2A), signal transducer and activator of transcription 3 (STAT3), matrix metalloproteinase-2 (MMP2), and others to induce tumor cell death or increase drug sensitivity." (PMID 39223142, 2024). "Since STAT3-MUC1 signaling is constitutively active in high-MUC1 tumor cells, we hypothesized that high-MUC1 cells are more sensitive to STAT3-inhibition." (PMID 38326371, 2024). "Additionally, hypoxia activates HIF1α via the IL-6/STAT3 signaling pathway, resulting in increased CD133 expression and the maintenance of tumor cell stemness." (PMID 38230205, 2024). "However, cholesterol and its derivates such as oxysterol, also promote cancer stemness, chronic inflammation and pro-tumour signalling pathways, such as MAPK and Wnt/b-catenin pathways and activation of STAT-3, which promotes EMT." (PMID 38751813, 2024). "FOSL1 triggers the activation of the IL-6/JAK/Stat3 signaling pathway, resulting in a malignant switch in breast tumor cells that leads to increased release of pro-angiogenic factors such as MMP-9, VEGF, and TGF-β from the tumor cells." (PMID 38791400, 2024). "Additionally, tumor-derived miR-6794-5p was delivered to THP-1-derived macrophages and induced M2 polarization by activating the JAK1/STAT3 pathway." (PMID 38521953, 2024). "We also compared mT4-Lyt2-Luc-LA tumour burden in wild-type and STAT3f/f CreLysM mice and found delayed tumour growth in mice that lacked STAT3 expression in myeloid cells." (PMID 39886125, 2024). "In the TME, a pro-tumor M2 macrophage polarization is promoted and sustained by a marked increase in immunosuppressive cytokine IL-10, which induces cell growth by activating JAK/STAT3, a COX-2 inductor signaling pathway." (PMID 38334650, 2024). "Our results demonstrate that neither persistent activation nor genetic ablation of STAT3 confers a selective growth advantage on tumor cells." (PMID 38573819, 2024). "In this study, we found that STAT3, one of downstream targets of FGFRs, was still activated upon Erdafitinib treatment in LUSC H520 cells, which might limit the anti-tumor activity of such drug." (PMID 39247610, 2024). "Moreover, the aberrant activation of STAT3 provides direct benefits within the tumor cell itself, and the added benefits of fibroblast reprogramming in the TME to support tumor growth and survival." (PMID 38464736, 2024). "Up-regulated the expression of IL-8, MMP2, MMP9, p-STAT3, and ZEB1 in tumor." (PMID 39906741, 2024). "Other than its known roles in promoting tumor progression, it has recently been discovered that IL6-dependent STAT3 signaling plays a central role in inflammation-mediated cancer, obesity or metabolic reprogramming, cancer stem cells, and pre-metastatic niche formation." (PMID 38320998, 2024). "Activated STAT3, NF-κB, JAK/STAT pathway, and CXCR-2 in tumor." (PMID 39906741, 2024). "Indeed, in the TSPO HIGH III cluster we observed a significant overexpression of the MES-like TAM tumor interaction genes OSM, OSMR, STAT3 and of CD44." (PMID 37697350, 2023). "Taken together, our results suggested that upregulation of CD40, CTLA4, ARG1, STAT3, IDO, and CD274, which were included in tumor inflammation signature, in the TME of KRASmut, could be characteristic of immune suppression." (PMID 36831441, 2023). "Suppression of CDK1 by fisetin reduced tumor stemness and phosphorylation of CDK1 and STAT3." (PMID 37743465, 2023).